CD44 (CD44 molecule (IN blood group))
Diseases named in the same sentence as CD44 in open-access papers (continued):
Sharing a sentence is not in itself a finding about the gene and the disease.
melanoma (continued). "In conclusion, the tumor suppressive miR-143-3p was identified as the most potent CD44 inhibitory miR, which affects growth characteristics of melanoma cells suggesting the implementation of miR-143-3p as as a potential anti-CD44 therapy of malignant melanoma." (PMID 31741714, 2019). "In this study, we investigated this hypothesis, and found that the CD44/HA axis fosters BMP4/7-dependent Id1/3 protein expression in melanoma cells through interactions between CD44 and BMPR." (PMID 30297743, 2018). "Thus, we next examined the roles of CD44 in these responses by comparing the metastasis of B16-F10 melanoma cells and TGF-β1 production in WT and CD44−/− mice." (PMID 30165890, 2018). "CD44 and MMPs MMP2 and MMP9 are implicated in the progression and metastasis of melanoma." (PMID 30157785, 2018). "By Western blot analysis we could observe that ABCB5 and CD44 are expressed in both melanoma cell lines; conversely, CD271 is expressed in A375 cells, while no protein band could be detected in BLM cells." (PMID 29330434, 2018). "We also found in a 2D screen of 51 mAbs, including AIIB2, against cell surface-associated molecules using the melanoma cell line HTB-66 as well as fresh melanoma, that the anti-CD44 mAb H4C4 blocks coalescence, and this observation was repeated in 4D reconstructions in the 3D Matrigel model." (PMID 28264026, 2017). "Several studies have indicated that CD44 is a CSC marker in various cancers including melanoma." (PMID 28137308, 2017). "HYAL2 has also been shown to directly cleave CD44, which may disturb the hyaluronan-CD44 interaction and release locally growing melanoma cells enabling the cells to spread." (PMID 27184066, 2016). "CD44 is highly expressed in IH cells, as shown by our genotypic and phenotypic analyses, and can be detected by immunohistochemistry in various normal and neoplastic tissues such as lymph nodes, melanoma, tumors of the testis." (PMID 27786256, 2016). "In a majority of all patients examined, melanoma cells stained positive for CD44." (PMID 24489649, 2014). "Therefore as a first step we determined the CD44 fingerprint of HT168M1 human melanoma cell line growing in vitro on different matrices, namely fibronectin, laminin, collagen and matrigel." (PMID 23342032, 2013). "The melanocytic and dysplastic nevi, in situ melanomas, superficially and deeply invasive melanomas and their lymph node metastases were analysed immunohistochemically for the amount of hyaluronan, its cell surface receptor CD44, hyaluronan synthases 1–3 and hyaluronidases 1–2." (PMID 23560496, 2013). "CD44 staining intensity displayed similar pattern of increased staining in premalignant lesions as hyaluronan, being increased in dysplastic nevi and in situ melanomas (p=0.013 and p=0.004, respectively) compared to benign nevi." (PMID 23560496, 2013). "Like hyaluronan, CD44 was strongly expressed in all lesions studied, more than 76% of the melanocytic cells being positively stained in all benign nevi, dysplastic nevi and in situ melanomas and in almost all superficial melanomas." (PMID 23560496, 2013). "With this method we examined the CD44 ASP of human melanoma cell lines (HT168M1, WM35, WM983B, A2058 and HT199) in culture to establish whether there is a pattern that is conserved across these genetically different tumours." (PMID 23342032, 2013). "For example, M14#5 cells express CD44 but not melanoma-associated proteoglycan/melanoma chondroitin sulfate proteoglycan (MPG/MCSP/NG2), while M14#11 cells express both." (PMID 23213537, 2012). "However, blocking CD44 activity in the absence of exogenous activating ligands did not alter the susceptibility of melanoma cells to MEKi treatment." (PMID 38942020, 2024).
melanoma (continued). "Furthermore, fibroblasts activated by melanoma cells showed upregulation of the MMPs’ expression mediators’ levels (pERK, p-p38, CD44, RUNX), enhanced secretion of lactate, several cytokines (IL8, IL6, CXCL1, CCL2, ICAM1), and proteins related to angiogenesis (GM-CSF, DPPIV, VEGFA, PIGF)." (PMID 35538545, 2022). "Correspondingly, the activation of Wnt/β-catenin pathway will activate the direct interaction of CD44 with cortactin and will enhance the transcription of CD44 and c-myc in indicating positive feedback of Wnt signaling-CD44 loop promoting cell adhesion, migration, and invasion of BC and melanoma." (PMID 36505828, 2022). "Furthermore, CD44+/CD24+ melanoma cells have been shown to have greater tumor-forming potential in vivo than CD44+/CD24–, suggesting that the increased malignant potential might be attributable to CD24 expression." (PMID 36013184, 2022). "A possible partially explanatory mechanism for this behavior may be that the V3 isoform binds to CD44 on the cell surface of melanoma cells, thus interfering with the interaction involving CD44 and the EGFR-ErbB2 complex, ultimately attenuating downstream oncogenic signals." (PMID 35454809, 2022). "The association between ABCB1 and CD44 was further proven by a study concluding that ABCB1 might interact with CD44 through the activation of extracellular signal-regulated protein kinase 1/2 (ERK1/2) and MAPK in the M14 ADR-resistant human melanoma cell line." (PMID 33801148, 2021). "However, the presence of CD44+ CTCs was associated with a poorer overall survival only in patients with melanoma but not with other tumors in the cohort." (PMID 34440558, 2021). "Notably, in RUNT KO melanoma cells, the expression of CD44 was also reduced." (PMID 32204402, 2020). "Thus, we can propose that inhibition or activation of the protein kinases such as AKT, HIPK2, AMPK, MET, JNK, HIF-1α, and CD44 by treatment with CDPs in the mouse melanoma model could involve the blocking of the substrate binding site as a molecular mechanism." (PMID 32793477, 2020). "Downregulated RNF128 activates Wnt signaling to induce cellular EMT and stemness by ubiquitinating and degrading CD44/CTTN, and RNF128 is a reliable diagnostic and prognostic biomarker, and a deeper understanding of RNF128 may contribute to the treatment of melanoma." (PMID 30832692, 2019). "The tumor-promoting properties of these transcriptional regulators, and the ability of the HA/CD44 axis to promote their expression in response to BMP stimulation, likely underlies the association between coordinate expression of Id1/Id3 and HAS2/HAS3/CD44, and reduced survival of melanoma patients." (PMID 30297743, 2018). "Interestingly, our group described how CD44 promotes rounded-amoeboid migration in melanoma." (PMID 27308633, 2016). "To decide whether the in vitro melanoma CD44 fingerprint is maintained in vivo despite the influence of the microenvironment, we compared the CD44 splicing pattern of several, genetically different human melanoma cell lines (A2058, HT199, WM35, WM983A, M35) growing on plastic or different matrices." (PMID 23342032, 2013). "Especially the staining of HYAL2 was changed in dysplastic nevi and melanomas compared to benign nevi, providing a logical explanation for the observed alterations in hyaluronan staining, but also suggesting a connection to the reduced staining of CD44 as previously reported." (PMID 23560496, 2013). "Finally, CS modification of CD44 (which occurs in melanoma) negatively regulates HA binding." (PMID 23213537, 2012). "First, CRISPR activation screens in melanoma cells identify functionally diverse regulators of TCR-specific cytotoxicity, including SAFB, KHDRBS1, MYC, CD44, WNT3A, WNT1 and others." (PMID 41946842, 2026). "In a B16F10 melanoma model, auranofin treatment increased lung tumor coverage, IL-10 serum levels, and FOXP3+CD44+CD4+ T cell frequencies." (PMID 41300507, 2025).
melanoma (continued). "For instance, CD44 and ALDH1A1 expressions are significantly higher in melanoma than in other skin cancers, suggesting a unique role in melanoma aggressiveness." (PMID 40867277, 2025). "As a methodology, SFD is able to reveal well-known proteins in melanoma exosomes that are immune-related and are also surface-expressed proteins, such as CD26 (DPP4), CD44, CALR, B7-H3 (CD276), CSF1, ICAM1, L1CAM, MICB, APOH, TIMP1, and CD39." (PMID 40805206, 2025). "The authors showed that melanoma cell lines A375 and BLM share the expression of the stem cell markers ABCB5 and CD44, but A375 cells uniquely expressed CD271 and exhibited melanosphere formation, a hallmark of stemness, unlike BLM cells." (PMID 40867277, 2025). "Through receptors such as CD44 and RHAMM, HA activates signalling pathways including MAPK/ERK that support melanoma cell survival and motility, and elevated HA–CD44 signalling is associated with more aggressive melanoma phenotypes." (PMID 41465475, 2025). "CD44 and CD133 identify CSCs in melanoma but show varying expression levels and clinical significance." (PMID 40867277, 2025). "Overexpression of miR-143-3p was shown to inhibit CD44 translation in the melanoma cell line BLM, which was accompanied by a decrease in proliferation, migration, and enhanced apoptosis of melanoma cells induced by daunorubicin in vitro." (PMID 39594665, 2024). "For example, a novel vaccine targeting CD133(+) CD44(+) MSCs in melanoma, expressing a 6kDa early secretory antigenic target (ESAT-6) and secreting interleukin (IL)-21, significantly suppressed melanoma growth and metastasis in mice, extending survival." (PMID 39611156, 2024). "In the melanoma anti-CTLA4 cohort, the AUC of CD44 was 0.8, indicating a higher predictive ability than any other marker, except MSI (AUC = 0.9)." (PMID 38590654, 2024). "A monoclonal antibody against CD44 (RG7356) in a Phase I clinical trial (NCT01358903) showed low clinical efficacy for patients with a variety of solid tumors, including melanoma." (PMID 39594665, 2024). "HA/CD44 interaction produces peroxynitrite and H2O2, which induces HA-mediated melanoma cell motility." (PMID 37107200, 2023). "In melanoma, low expression of RNF128 activates Wnt/β-catenin signaling to induce cellular EMT and stemness and protects CD44 and cortactin from degradation mediated by ubiquitination." (PMID 36644633, 2022). "This supports the idea that tumor cells in vivo reside in distinct redox states, and it is interesting to note that from nine high CD44 and low NRF2 stained samples a total of six samples were derived from melanoma metastasis." (PMID 34951143, 2022). "In contrast to melanoma observation, compared to A549 spheroid cultures, higher basal intracellular expression of MITF in CD44+ and CD133+ spheroid cultures of H1299 cells were well correlated with their increased cellular FAM3C expression." (PMID 35563313, 2022). "We also saw a higher infiltration of melanoma-specific hGP100TCR+CD8+ T cells that were PD-1+ and CD44+." (PMID 36106631, 2022). "To elucidate new targets of carotenoid-rich Goji extracts, we focused on CD44 and CD105 membrane markers, two molecules expressed on human dermal fibroblasts and as well on melanoma cells, with deep implications in redox signaling and stemness." (PMID 33440679, 2021). "As cancer stem cells (CSCs) are often associated with dormancy, slow growth, and drug tolerance, we measured the common melanoma CSCs biomarkers (CD271, CD44, CD34, and aldehyde dehydrogenase activity) to determine if the isolated persisters are CSCs." (PMID 34822435, 2021). "B16-F10 melanoma cells with expression of CD133, CD44, and CD24 generated the fastest tumor formation compared to cells with other phenotype, despite that they were implanted in five times smaller density." (PMID 33424978, 2020). "Similar to human melanoma, equine melanomas are typically positive for S100, PCNA, HMB‐45, Ki‐67, T‐311, and CD44 by immunohistochemistry." (PMID 32652526, 2020).
melanoma (continued). "In melanoma, RNF128 interferes with the ubiquitination and degradation of CD44 and cortactin proteins, activates the Wnt pathway, and promotes the cellular EMT and stem cell development." (PMID 33195233, 2020). "In summary, our findings, including reduced osteopontin, bone sialoprotein and CD44, supported RUNX2 involvement in promoting melanoma cell osteotropism." (PMID 32204402, 2020). "Examples include prostate cancer (prostate-specific membrane antigen, known as PSMA); oral cancer (CD44); lung cancer (delta-like protein 3); glioblastoma (CD133); and melanoma (CD146)." (PMID 33202648, 2020). "And these cells produced elevated levels of IL-17A and IFN-γ and developed a distinct memory phenotype with elevated expression of CD44 and CD62L during response to established melanoma while untreated cells mainly presented effector phenotypes in melanoma." (PMID 30800130, 2019). "The increase of CD44 after FGF2 treatment enhanced the directed migration of several cell types, including periodontal ligament cells, endothelial cells, and melanoma cells." (PMID 31191685, 2019). "Immunohistochemical staining was performed to detect the expression of iNOS and hTERT, p-p65, Epcam, CD44, PCNA in mice with melanoma xenografts." (PMID 30717768, 2019). "Low levels of RNF128 were shown to induce melanoma cell EMT and promote lung metastasis through the Wnt/β-catenin pathway via the ubiquitination of CD44 and CTTN." (PMID 30832692, 2019). "To further investigate the mechanism of the combinational effect related to melanoma stem cell traits, we determined the expression levels of cancer stem cell (CSC)-related markers, including Epcam, CD44, OCT4 and c-kit." (PMID 30717768, 2019). "Taken together, these results indicate that RNF128 participates in the positive feedback for the Wnt signaling-CD44 axis and promotes cell EMT and stemness in melanoma cells." (PMID 30832692, 2019). "To further explore the relationships between RNF128, CD44, and CTTN, we detected their expression in 30 pairs of melanoma and matched peritumoral tissues." (PMID 30832692, 2019). "β-catenin is then translocated to the nucleus of melanoma cells and activates TCF/LEF-mediated gene transcription, resulting in up-regulation of the adhesion molecule CD44." (PMID 30285678, 2018). "We therefore conclude that the CD44/HA axis can potentiate the ability of BMP4/7 to activate Id1 and Id3 expression in melanoma cells, thereby contributing to poor prognosis." (PMID 30297743, 2018). "We found that both A375 and BLM melanoma cells express the surface stem cell markers ABCB5 and CD44, as evaluated by Western blotting and by immunofluorescence analysis; on the other hand the stem cell marker CD271 is expressed only in A375 cells." (PMID 29330434, 2018). "To further confirm the role of fascin in regulation of melanoma stemness, we examined the expression level of CD44 in fascin knockout (KO) and control WM793 cells and found that CD44 level was significantly reduced in fascin KO cells." (PMID 29970086, 2018). "Wnt5a signaling results in acyl protein thioesterase 1 (APT1) mediated depalmitoylation of pro-metastatic cell adhesion molecules CD44 and MCAM, resulting in increased melanoma invasion." (PMID 29648538, 2018). "It was concluded that both melanoma and SCC show CD44-high phenotype suggesting that CD44 is a candidate for targeted therapy of skin cancers aiming at cancer stem cells." (PMID 27505250, 2016). "To further prove the potential of ABCB5 as a CSC marker in murine melanoma cells, we sorted B16F10 (CD44+CD133+CD24+) by FACSAriaTM III which have been proved to have biological characteristics of CSC." (PMID 26910836, 2016). "Putative CSCs have been isolated from many tumour types including leukaemia, melanoma, and various carcinomas using markers such as CD133, CD24, CD44, and ALDH1." (PMID 26606927, 2015). "The few targets we were able to detect on melanoma cells were ErbB3, CD33 and CD44, confirming previous observations." (PMID 24489649, 2014).
melanoma (continued). "We have previously shown that fastuosain, a cysteine-protease from Bromelia fastuosa protected mice against murine melanoma B16F10-Nex2 subcutaneous development, mainly by reduction of CD44 expression, which led to decreased tumor cell invasion." (PMID 24788523, 2014). "The results of our study show that melanoma cells display a unique composition of cell surface antigens, including ErbB3, IGF-1-R, CD44 and ICAM-1." (PMID 24489649, 2014). "In these analyses, we were able to confirm expression of transcripts specific for CD63, ErbB3, CD44, and IGF-1-R in melanoma cells and melanoma cell lines in all samples tested." (PMID 24489649, 2014). "In our data, the staining pattern of the lymph node metastases resembled that of the primary tumor, but the amount of CD44 and HAS1 were further reduced in the metastases compared to deep melanomas." (PMID 23560496, 2013). "The efficacies of the various liposomal nanoDDSs were evaluated by quantifying their cytotoxic effects against cell lines with varying levels of CD44/CSPG expression and in a B16F10 mouse melanoma model system." (PMID 23213537, 2012). "We examined the expression of CD133, CD44, CD24, and ABCB5 during tumorigenesis of B16 melanoma cells transfected with empty or GDF3-expressing vectors." (PMID 20950440, 2010). "Mouse melanoma CSC-like cells have a high degree of tumorigenicity and express CD133, CD44, and CD24." (PMID 20950440, 2010). "However, the role of CD44 and CD133 as melanoma CSC markers remains controversial, with studies indicating that both CD133+ and CD133− subsets can initiate tumors." (PMID 40867277, 2025). "In contrast, the protein expression of CD44 was not significantly altered in either melanoma cell line and similarly to it no change was detected in melanocytes." (PMID 41465475, 2025). "CD44, another stemness marker, is expressed across various CSC populations, including melanoma." (PMID 39611156, 2024). "Analyses of the respective expression levels of CD44 and miR-143-3p in human melanocytic nevus and dermal melanoma samples demonstrated medium to high levels of CD44 without correlation with tumor grading or stage." (PMID 39594665, 2024). "In addition, a moderate positive correlation is observed between ENG and MCAM (Melanoma Cell Adhesion Molecule), as well as between CD14 and CD44." (PMID 39594703, 2024). "By means of in vitro and in vivo studies, it has been pointed out that lipid nanoparticles coated with hyaluronic acid (HA), a well-known ligand of CD44, and loaded with the taxane chemotherapy drug paclitaxel (PTX-loaded HA-SLNs) suppress the subpopulation of CD44+ melanoma cells." (PMID 39199632, 2024). "Additionally, DCP-IL-12/FLT3L strongly expanded cDCs and CD44+CD62L− T effector cells in tdLNs, which aligns with findings in the B16F10 melanoma model." (PMID 37996514, 2024). "Blocking of CD44-mediated adhesion to HA by Pep-1; no reduction in melanoma cell proliferation in vitro or growth in vivo; significant reduction in lung metastasis incidence and increased survival observed following a single intravenous injection of Pep-1." (PMID 39594665, 2024). "HPD–siRNA complexes were efficiently taken up by B16-F10 melanoma cells overexpressing CD44, but not by normal fibroblasts." (PMID 39594665, 2024). "Chondroitin sulfate-modified CD44 (110 kDa) in mouse melanoma promotes melanoma cell motility (not adhesion and spread) on type I collagen." (PMID 35936713, 2022). "Knock-down of CD44 in breast and melanoma tumors, and targeted knock-down of COX2 in non-transformed healthy myeloid cells and mouse embryonic fibroblasts were also able to increase the numbers and functional activation of NK cells." (PMID 36359827, 2022). "Furthermore, analysis of human melanoma samples confirmed a vice versa relationship of NRF2 and CD44 expression." (PMID 34951143, 2022).